IL1F10 (interleukin 1 family member 10)
Description:
Cytokine with immunomodulatory activity. Alone, does not induce cytokine production, but reduces IL22 and IL17A production by T-cells in response to heat-killed Candida albicans. Reduces IL36G-induced production of IL8 by peripheral blood mononuclear cells. Increases IL6 production by dendritic cells stimulated by bacterial lipopolysaccharides (LPS). Ligand for IL-36R/IL1RL2.
Synonyms: IL-1F10; IL-1HY2; IL-38; IL1HY2; FKSG75; IL1-theta; MGC11983; MGC119832; MGC119833; FIL1-theta
Tractability: Antibody: UniProt places it where antibodies can reach, with high confidence; its Gene Ontology location is reachable by antibodies, with high confidence.
Gene: Protein-coding gene on chromosome 2 (113,067,970 to 113,075,843, forward strand). Ensembl gene ENSG00000136697.
Subcellular location: Cytoplasm; Secreted
Pathways (Reactome):
Immune System: Interleukin-36 pathway; Interleukin-38 signaling
Gene Ontology:
Molecular function: protein binding; cytokine activity; interleukin-1 receptor binding
Biological process: cellular response to lipopolysaccharide; cytokine-mediated signaling pathway; immune response; inflammatory response
Cellular component: cytoplasm; extracellular region
Genetic constraint (gnomAD): Loss-of-function variants: 17 observed, 16.1 expected, observed/expected ratio (o/e) 1.06, 90% interval 0.72 to 1.58. The upper end of that interval is the gene's LOEUF score, 1.58, which puts it in group 6 of 6, group 1 being the genes least tolerant of losing a copy. Missense variants: 184 observed, 180.13 expected, observed/expected ratio (o/e) 1.02, 90% interval 0.9 to 1.15. Synonymous variants: 75 observed, 66.32 expected, observed/expected ratio (o/e) 1.13, 90% interval 0.94 to 1.37.
Homologues: Orthologues: chimpanzee IL1F10 (98% identical), macaque IL1F10 (94% identical), dog IL1F10 (88% identical), rat Il1f10 (82% identical), mouse Il1f10 (82% identical), guinea pig IL1F10 (78% identical), zebrafish il1b (24% identical), zebrafish il1fma (19% identical). Paralogues in human: IL36RN (41% identical), IL1RN (39% identical), IL37 (30% identical), IL36A (26% identical), IL36G (26% identical), IL36B (25% identical), IL1B (20% identical).
Diseases named in the same sentence as IL1F10 in open-access papers:
IL1F10 is named in the same sentence as 153 diseases in open-access papers, as found by Europe PMC text mining. Sharing a sentence is not in itself a finding about the gene and the disease. The quoted sentences say what the papers report.
psoriasis (26 papers, 2018 to 2025). An autoimmune condition characterized by red, well-delineated plaques with silvery scales that are usually on the extensor surfaces and scalp. "Using an imiquimod-induced psoriasis model, they demonstrated that local Il36rn, but not Il38 levels, were increased in the inflamed skin following topical application of AldaraTM and disease severity and progression was comparable between Il1f10−/− mice and wild-type littermate controls." (PMID 31231388, 2019).
rheumatoid arthritis (24 papers, 2015 to 2025). A chronic, systemic autoimmune disorder characterized by inflammation in the synovial membranes and articular surfaces. "Several studies have also identified correlations between polymorphisms in the IL-38 gene, IL1F10, and the incidence of inflammatory diseases such as psoriatic arthritis, ankylosing spondylitis, and rheumatoid arthritis." (PMID 40057603, 2025). "IL-1 family includes IL-38 (IL-1F10) and the subfamily of IL-36 and is the central mediators of inflammatory diseases, including pustular psoriasis, atopic dermatitis, rheumatoid arthritis, and gut inflammation." (PMID 30643810, 2018).
Arthritis (14 papers, 2006 to 2025). Inflammation of a joint. "As a first approach to investigate expression of new IL-1 family members during arthritis, we examined IL-1F5 to IL-1F10 mRNA expression by RT-PCR in joints of mice with CIA and in synovial biopsies from patients with RA or OA." (PMID 16646978, 2006).
Sepsis (13 papers, 2020 to 2025). Sepsis is defined as life-threatening organ dysfunction caused by a dysregulated host response to infection. "IL1F10 belongs to the interleukin-1 (IL-1) family of cytokines and in particular IL1F10 has been suggested being of diagnostic and prognostic value as clinical sepsis biomarker." (PMID 38283341, 2023). "Distinct patterns emerged with increased SYT13 and IL1F10 levels in plasma samples from sepsis patients, while A2M levels were decreased when compared to the level detected in plasma samples from trauma patients." (PMID 38283341, 2023). "At the early time point, SYT13 and IL1F10 displayed a minimum 2-fold shift increase in expression levels in sepsis patients when compared to trauma patients." (PMID 38283341, 2023). "SYT13 and IL1F10 emerged as potential early sepsis biomarkers, while reduced levels of A2M were indicative of both trauma-induced inflammation and sepsis conditions." (PMID 38283341, 2023). "To validate our findings, we extended the number of plasma samples for trauma (n = 23) and sepsis patients (n = 23) and performed quantitative ELISA to measure the contents of A2M, IL1F10, SYT13, and TREM1 in these samples at three time points (day 0, 3 and 5)." (PMID 38283341, 2023). "A2M, IL1F10, SYT13, and TREM1 emerge as compelling biomarkers for sepsis and trauma based on their distinct roles in immune response modulation." (PMID 38283341, 2023). "For early detection of sepsis patients from trauma, the AUC for SYT13 is 0.8913 and for IL1F10 is 0.9058." (PMID 38283341, 2023). "Our analysis showed enhanced levels of SYT13, IL1F10, and S100A10 cytokines in early sepsis patients, while TREM1 levels in trauma patients increased gradually over time." (PMID 38283341, 2023). "Interestingly, IL1F10 positivity was also observed in SYT13-negative samples, suggesting the complexity of biomarker interactions in sepsis cases." (PMID 38283341, 2023). "A similar analysis compared early sepsis samples with positive and negative IL1F10 2-fold shift outcomes." (PMID 38283341, 2023). "To conclude, our research emphasizes the potential of A2M, IL1F10, SYT13, and TREM1 as a composite set of biomarkers for distinguishing between non-infected trauma and sepsis patients." (PMID 38283341, 2023).
myocardial infarction (10 papers, 2020 to 2025). Gross necrosis of the myocardium, as a result of interruption of the blood supply to the area, as in coronary thrombosis. "One common upSNV is present in the 5′UTR region of the IL1F10 gene, a susceptibility locus for myocardial infarction (MI)." (PMID 35387445, 2022).
atherosclerosis (8 papers, 2016 to 2025). A disease characterized by the build-up of fatty material and calcium deposition in the arterial wall resulting in partial or complete occlusion of the arterial lumen. "In addition, we evaluated the potential relationship between HNF1A rs1183910, LEPR rs4420065, GCKR rs1260326, NLRP3 rs12239046, IL1F10 rs6734238, PPP1R3B rs9987289, ASCL1 rs10745954, HNF4A rs1800961 and SALL1 rs10521222 polymorphisms and CV events or subclinical atherosclerosis in RA patients." (PMID 27534721, 2016).
coronary artery disease (5 papers, 2015 to 2023). "Notably, the polygenic analysis revealed that rs6734238 in the IL1F10/IL1RN locus was found to be significantly associated with coronary artery disease." (PMID 37382260, 2023).
breast carcinoma (3 papers, 2023 to 2026). "In the METABRIC data set, expression of IL1F10, encoding IL-38 negatively correlated with survival in patients with breast cancer." (PMID 39209451, 2024).
hyperlipidemia (3 papers, 2021 to 2022). "SNPs associated with IL1F10 are associated with serum C‐reactive protein (CRP) concentrations in a genome‐wide association study, and recombinant IL‐38 inhibits CRP and IL‐1β production by PBMC from patients with hyperlipidemia." (PMID 33125159, 2021). "In patients with hyperlipidemia, IL1F10 mRNA in PBMC and IL‐38 in serum were elevated compared to healthy controls." (PMID 33125159, 2021). "The gene expression of IL1F10 has been detected in PBMC of STEMI and hyperlipidemia patients." (PMID 33125159, 2021).
Insulin resistance (3 papers, 2021 to 2022). Increased resistance towards insulin, that is, diminished effectiveness of insulin in reducing blood glucose levels. "IL1F10/IL-38 and IL1RN variants (rs6759676 and rs4251961) in partial LD with the lead SNP (r2LD:0.10 and 0.61) have been recently reported to be protective against the development of insulin resistance." (PMID 33517400, 2021).
Hepatic steatosis (2 papers, 2013 to 2025). Steatosis is a term used to denote lipid accumulation within hepatocytes. "In patients with advanced hepatic steatosis (score ≥ 3), chemokine (C-X-C motif) ligand 14 (CXCL14), interleukin-1 family member 10 (IL1F10), and interleukin 8 receptor β (IL8RB) had a significant differential expression (P ≤ 0.05) as compared to those with mild steatosis (score ≤ 2)." (PMID 23661906, 2013).
rheumatic diseases (2 papers, 2018 to 2021). "In humans, polymorphisms in the IL1F10 locus are associated with rheumatic diseases and IL-38 expression or serum levels have been recorded in some autoimmune pathologies, but overall few data are available concerning the role of IL-38 in inflammatory diseases." (PMID 29554104, 2018).
skin inflammation (2 papers, 2021 to 2024). "Il1f10 is also constitutively expressed in healthy mouse epidermis, and significantly decreased during Aldara (5% IMQ)-induced skin inflammation." (PMID 33796114, 2021).
steatosis (1 paper, 2013). Increased lipid within the cytoplasm of cells. "In addition, IL8RB and IL1F10 levels were positively correlated with a degree of steatosis (P ≤ 0.05)." (PMID 23661906, 2013).
tumor (26 papers, 2017 to 2026). "Analysis of differential expression between GC tumor tissues and normal tissues revealed upregulated SERPINE1, IL1F10, IGFBP1, and ITIH2, whereas C6, GCG, GRP, and APOD were downregulated." (PMID 41551463, 2026). "Further analysis of the differential expression of IL-1 family and related genes in normal tissues and HPV- and HPV+ tumor tissues revealed that IL-1α, IL-1β, IL1R1, IL1R2, IL1RL1, IL1RAP, IL1F10, IL-18 and CASP1 were highly expressed in HPV- tumors." (PMID 39461030, 2024). "In tumor tissues, IL-1α, IL-1β, IL1R1, IL1RL1, IL1F10, IL33, CASP1, and AIM2 are highly expressed." (PMID 39461030, 2024).
infection (8 papers, 2020 to 2025). The state of being infected such as from the introduction of a foreign agent such as serum, vaccine, antigenic substance or organism. "While the levels of TREM1 are found up-regulated during the course of the disease we found a negative correlation for SYT13 and IL1F10 which implicate that their downregulation during the course of infection may negatively impact the host response to infection." (PMID 38283341, 2023).
head and neck tumors (1 paper, 2024). "In this study, it was found that IL-1α, IL-1β, IL1R1, IL1RL1, IL1F10, IL33, CASP1, and AIM2 were highly expressed in head and neck tumors, while IL1RN, IL1RAPL1, IL1RAPL2, IL18BP, IL18R1, and IL18RAP were low in expressed, which is consistent with previous literature." (PMID 39461030, 2024).
IL1F10 also shares sentences with these, for which no sentence is quoted: autoimmune disease (17 papers); cancer (15); systemic lupus erythematosus (14); inflammatory bowel disease (11); psoriatic arthritis (10); colorectal cancer (9); COVID-19 (9); asthma (8); chronic hepatitis B (8); lung carcinoma (8); non-small cell lung carcinoma (8); viral infections (8); Autoimmunity (7); colitis (7); cardiovascular disease (6); inflammatory skin disease (6); allergic asthma (5); ankylosing spondylitis (5); Atopic Dermatitis (5); Crohn disease (5); infectious disease (5); ischemic stroke (5); metabolic disease (5); osteoarthritis (5); primary Sjogren’s syndrome (5); ulcerative colitis (5); diabetes (4); gestational diabetes mellitus (4); gouty arthritis (4); lung adenocarcinoma (4).
A further 106 diseases each share a sentence with IL1F10 in 3 papers or fewer.